CXCL9 (C-X-C motif chemokine ligand 9)
Diseases named in the same sentence as CXCL9 in open-access papers (continued):
Sharing a sentence is not in itself a finding about the gene and the disease.
tumor (continued). "Importantly, this study shows that NE can affect the secretion of the chemokine CXCL9 and the immunosuppressive metabolite ADO in tumour cells by regulating the WNT7A/β-catenin signalling pathway, thereby reducing the chemotaxis and function of CD8+ T cells, resulting in anti-PD-1 mAb resistance." (PMID 36646807, 2023). "CXCL9 can be secreted by a variety of cells, including immune cells (T lymphocytes, NK cells, dendritic cells, macrophages, and eosinophils) and non-immune cells (endothelial cells, tumor cells, and fibroblasts)." (PMID 36479091, 2022). "As tumor CXCL10 and CXCL9 concentrations were correlated with the quantity of intratumoral lymphocyte and CD3 + T cells, we wanted to confirm whether the plasma levels of these cytokines would give some guidance to the tumor lymphocyte counts." (PMID 35927313, 2022). "When examining the factors that could contribute to CD8+ Teff tumor recruitment, we found that CD8+ Teffs expressed the chemokine receptors CXCR3 and CXCR4, while the TME produced abundant CXCL9 and CXCL12, which are the key chemokines known to bind CXCR3 and CXCR4, respectively." (PMID 35552271, 2022). "Results suggest that AKAP12, APOL3, CXCL13, CXCL9, GBP4, and LRIG1 may act as tumor suppressors." (PMID 35677536, 2022). "In addition, higher expression of LCK has been confirmed in this work that it also upregulated the expression levels of CXCL9, CXCL10, and CXCL 11, which were reported to initiate a chemokine network to contribute to the generation of a “hot” (or T-cell–inflamed) tumor microenvironment." (PMID 36561315, 2022). "Interestingly, injection of recombinant IFN-γ beside the tumor was able to restore Cxcl9 but not Cxcl10 expression in B16-F10 tumors." (PMID 35103755, 2022). "The relationship between the CXCL9,10,11/CXCR3 pathways and PD-1/PD-L1 is a vital area of research, and combining this pathway with other immunotherapies improves the efficacy of tumor immunotherapy by enhancing the inhibition of tumor progression through multiple mechanisms." (PMID 36479091, 2022). "Therefore, whether LCK may promote the formation of TLSs and increase the anti-tumour function of TLSs through N1-TAN induction of CCL3, CXCL9 and CXCL10 aggregation remains to be further investigated." (PMID 36291944, 2022). "Hence, PC7A in nanovaccine activates STING pathway and CXCL9 in tumor derived leukocytes but not tumor cells." (PMID 35623658, 2022). "This provides evidence that high expression of CXCL9 and CXCL10 in the intra-tumor environment of the body is significantly correlated with a high density of CD8+ T cells and that increased selective expression of CXCL9 and CXCL10 in Treg cell-depleted tumors may serve as a potential immunotherapy." (PMID 36479091, 2022). "In the current study, we found that the expressions of CXCL9 and CXCR3 mRNA increased significantly in the lungs of Abt-Kras mice compared to paired controls as tumour progressed, and this may be the main reason for the constant amount of NK cells and CD8+T cells in their lung." (PMID 36033391, 2022). "Furthermore, inhibition of LINC00152 may increase the number of tumor-infiltrating CD8+ T cells and promote the expression of CXCL9, CXCL10, and C-X-C Motif chemokine receptor 3 (CXCR3) in xenograft tumors, thereby achieving the goal of tumor suppression." (PMID 35402261, 2022). "It was shown that CXCL9, which is the ligand with the lowest affinity for CXCR3, has the function of regulating immune cell migration, differentiation, and activation, with contribution to tumor suppression, which accounts for the suppression of CXCL9/CXCR3 on GC." (PMID 33763365, 2021). "In addition, CXCL10, CXCL9, and CXCL11 production is induced in the tumor microenvironment, which recruits cytotoxic lymphocytes (CTLs) and reduces tumor angiogenesis, inducing further tumor death." (PMID 33807260, 2021).
tumor (continued). "Other chemokines upregulated in either the tumour or infiltrating immune cells by CHK1i+LDHU, including CCL5 that directly recruits Tregs or CXCL9, CXCL10, CXCL11 that recruit activated effector, T, NK and NKT cells, as well as Tregs, may also be responsible for the accumulation of Tregs." (PMID 34359633, 2021). "Considering that species in Fusobacterium genus was one of the mucosal bacteria that promoted tumor development, this could partially explain why the chemokine CXCL9 could not serve as a powerful independent predictor of our CRC patient survival." (PMID 34539647, 2021). "In contrast, serum CXCL9 may not specifically guide CD8+ T cells homing to the tumor microenvironment." (PMID 34680466, 2021). "In addition, only CXCL9–12 and 14 expression varied significantly with HNSC tumor stage." (PMID 34247149, 2021). "CXCL9 has been previously reported to be transcribed and translated by perivascular macrophages and pericytes in the perivascular microenvironment of CNSL, where it may support the recruitment of tumor-infiltrating lymphocytes." (PMID 33841320, 2021). "Finally, 8 genes related to anti-tumor immunity were obtained, which were APOL3, CCL5, CD8A, CD8B, CXCL9, GZMA, GZMK and PRF1.We found that the m6A regulatory factors YTHDC1, YTHDC2, and WTAP were positively correlated with m6A, while IGF2BP3 was negatively correlated." (PMID 34737950, 2021). "In addition, the deficiency of MettL3 or Mettl14 in tumors results in enhancing cytotoxic tumor-infiltrating CD8+ T cells, and increasing the secretion of IFN-c, Cxcl9 and Cxcl10 in TME in vivo, which proves that the immune system and tumor microenvironment have metastasized in tumor m6A mRNA." (PMID 35069586, 2021). "MSI tumor samples displayed a peculiar cytokine profile compared to MSS tumors overexpressingchemokine (c-c motif) ligand (CCL-) 5, chemokine (C-X-C motif) ligand (CXCL-) -8, CXCL9, interleukin (IL-)-1β, CXCL10, IL-16, growth-regulated protein α (GROα), and IL-1 receptor agonist (IL1-ra)." (PMID 34072037, 2021). "Increased secretion of IL-6, TNFα, CCL2, CCL5, CXCL9 and GM-CSF, which are pro-inflammatory factors combined with decreased secretion of anti-inflammatory factors including IL-4, IL-28A, CCL24, CXCL12 and SCF from infected HEL299 fibroblasts, is expected to be tumor-promoting and enhance metastasis." (PMID 34575976, 2021). "Moreover, we observed that the production of CCL4, CCL5, CXCL9 and CXCL10 chemokines was induced by the co-culture of murlentamab-opsonized SKOV3-R2+ tumor cells with both M0 and TAM-like MDMs, while the normal fucosylated form 3C23K-CHO did not demonstrate any effects." (PMID 33924378, 2021). "Notably, the CXCL9/CXCL10/CXCL11/CXCR3 axis recruits cytotoxic lymphocytes, NK cells, NKT cells, and macrophages to infiltrate tumor tissue and increases cytotoxic activity against tumor cells." (PMID 33763074, 2021). "In contrast, N1 TANs produce chemokines, such as C-C motif chemokine ligand 3 (CCL3, CXCL9, CXCL10), to recruit CD8+ T cells to TME and secrete cytokines (e.g., IL-12, TNF-α, and GM-CSF) to activatethe cytotoxicity of CD8+ T cells, thus providing anti-tumor effect." (PMID 34359674, 2021). "The lack of decrease in number of tumor-infiltrating CD4+ T cells could be attributable to increased expression of Cxcl9 that was observed in Siah2−/− tumors, which could increase T cell recruitment, compensating for decreased CD4+ T cells proliferation." (PMID 31911617, 2020). "A recent review reports that the CXCL9/CXCL10/CXCL11/CXCR3 axis is responsible for angiogenesis inhibition, and the activation and migration of immune cells such as cytotoxic lymphocytes and natural killer cells into the tumor microenvironment, to prevent tumor progression in BCa." (PMID 33003392, 2020).
tumor (continued). "Furthermore, IFNγ, produced by activated CTLs and abundant in inflamed tumours, can induce CXCL9 and CXCL10 secretion in various intermediary cells, including tumour-infiltrating myeloid cells, which may enhance the role of CXCR3 in homing." (PMID 33046212, 2020). "Furthermore, as cytokines can assist tumor progression, targeting IL-4, IL-13, IL-10, TGF-β, and CXCL5 or enhancing IFN-γ and some chemokines (e.g., CCL2, CCL3, CXCL9, CXCL10) may inhibit tumor invasion and metastasis." (PMID 32346605, 2020). "CXCL9 is secreted by various types of cells, including immune cells (e.g., macrophages, NK cells, dendritic cells, T lymphocytes), and non-immune cells (e.g., tumor cells and endothelial cells)." (PMID 32974144, 2020). "CXCL9/10/11, involved in the establishment of the CXCL9/10/11-CXCR3 axis in the tumor microenvironment, is a chemokine that activates T cells, which could regulate the differentiation, activation and migration of immune cells and effectively inhibit tumor growth." (PMID 33317597, 2020). "Furthermore, DC_c1 cells might have functional alteration and enhanced lipid utilization due to the remodeling of TME as the increased expression of CXCL9, IDO2, APOA2, and APOE compared to their non-tumor counterparts." (PMID 33298893, 2020). "Therefore, we investigated whether CXCL5, CXCL9, and CXCL10 expression was correlated with immune infiltration levels in GC using the Tumor Immune Estimation Resource (TIMER) database." (PMID 33323542, 2020). "CXCL9, CXCL10, and CXCL11 were found to recruit CD4+ and CD8+ lymphocytes, while CXCL13 could specifically attract T regulatory and Th2 lymphocytes into the tumour microenvironment." (PMID 31913856, 2020). "Due to the high expression of CXCR3-B on endothelial cells and the angiostatic effect of CXCL10, CXCL9, and CXCL4, it was proposed that the CXCR3-B variant could be responsible for this negative impact on tumor angiogenesis." (PMID 31216755, 2019). "Interestingly, the anti-tumor response to the inhibition of LIF was blunted in the CXCL9−/− mice but not in the CCL2−/− mice." (PMID 31186412, 2019). "For example, CXCL9 and CXCL10 induce effector Th1/Th17 cells and CXCL11 drives a Treg and Th2-biased effector cell polarization upon activation of CXCR3 on CD4+ T cells, while they upregulate tumor cell-related proteins that are beneficial for their survival, such as PD-L1." (PMID 31216755, 2019). "On the one hand, the CXCR3 chemokines, especially CXCL9 and CXCL10, facilitate the recruitment of CXCR3-positive Th1, NK, and NKT cells as well as cytotoxic T lymphocytes to the tumor microenvironment, which trigger the development of a tumor-suppressive immune milieu." (PMID 31482487, 2019). "Indeed, evidence in patients with ovarian cancer demonstrated that the increased expression of CXCL9 and CXCL10 correlates with an increased number of tumor-infiltrating CTL and a high CD8+/regulatory T cells ratio that lead to a reduction in cancer metastasis and to a better prognosis." (PMID 30319638, 2018). "Since CXCL9 and CXCL10 constitute two major molecules for effector T cells infiltration, it is speculated that combination of elemene and gefitinib might have an additional effect on enhancing anti-tumor T cell response." (PMID 30555330, 2018). "Tumor upregulated chemokines included the followings: CXCL5 (138 fold increase); CCL25 (70 fold increase); CXCL11 (26 fold increase); CXCL6 (20 fold increase); CXCL1 and CXCL10 (11 fold increase); CXCL3 (8 fold increase); and CXCL9, CXCL2, and CCL3L1 (6 fold increase)." (PMID 29088818, 2017). "qPCR revealed that the triple treatment resulted in the highest expression of mRNA for the T cell specific chemokines CXCL9 and CXCL10 in tumors, suggesting that these two chemokines might be responsible for the enhanced infiltration of CD4+ and CD8+ T cells in the tumor tissues after treatment." (PMID 28881713, 2017).
tumor (continued). "To further understand the role of adaptive immunity in the tumor tissue, we investigated the impact of RRS on tumor weight and on immune suppression markers (Foxp3, CCL22), as well as markers for anti-tumor immunity (Granzyme B, CCL5, IFN-γ, CXCL9, CXCL10 and CXCL11)." (PMID 28603578, 2017). "Furthermore, three of the prognostic cytokines/chemokines, CXCL9, IL-5, and TNF, when expressed at an increased level in specific tissue or cellular environment, may confer a downregulatory effect on tumor growth." (PMID 25825910, 2015). "Moreover, IL-17-producing αβ T cells stimulate the release of several cytokines (such as IL-6, IL-12, CXCL9, and CXCL10) by immune or cancer cells, leading to DC maturation or effector T cell recruitment to the tumor, and as a consequence, to an increase of the anti-tumor immunity." (PMID 25538706, 2014). "Thus, CXCL9, CXCL10, CXCL16, CCL5, and CX3CL1 can be used to efficiently mobilize CTLs from regional lymph nodes to tumor tissues with an objective to enhance CTL-mediated tumor destruction." (PMID 24966464, 2014). "Further studies showed that the full potency of CCL21-mediated anti-tumor response required the induction of IFN-γ, MIG/CXCL9 and IP-10/CXCL10 in concert, as neutralization or depletion of any one of these cytokines led to a decrease in the frequency of CXCR3+ve T cells and CD11c+ve DC in the tumor." (PMID 24810425, 2014). "CXCR3, which is present on activated MO/MAs and on activated T cells, binds several rIFN-γ1b- induceable chemokines, including CXCL9/Mig, CXCL10/IP-10, and CXCL11/I-TAC These chemokines might facilitate recruitment of activated leukocyte subsets to the tumor site." (PMID 16603073, 2006). "Hence, an increase in IFN-γ at the tumour site of CCL19-treated mice could explain the relative increases in CXCL10/IP-10 and CXCL9/MIG." (PMID 16598185, 2006). "Moreover, studies have shown that tumor-derived INHBA can dampen the response to immune checkpoint blockade by suppressing interferon-γ (IFN-γ) pathway, reducing programmed death-ligand 1 (PD-L1), and impairing T-cell chemokines secretion like C-X-C motif chemokine ligand 9/10 (CXCL9/10)." (PMID 41449244, 2025). "Therefore, AAV directed production of CXCL9 at the tumor site, independent of LIF expression, may be applicable to a broader range of GBM patients." (PMID 38997283, 2024). "Therefore, we stained tumor sections for Cxcl9 and Cxcl10 from untreated KPC2a-bearing mice and mice treated with αPD-L1 or CD40 agonist as such therapies may enhance IFNγ, which induces Cxcl9/Cxcl10." (PMID 36472588, 2023). "Moreover, CXCR3, which is the corresponding receptor of Cxcl9 and Cxcl10, is expressed by stem-like CD8+ Tpex cells and functions in CD8+ T-cell migration and positioning within tumors, as reported by prior studies, was significantly upregulated in CD8+ T cells after LDRT treatment of tumor." (PMID 38001101, 2023). "However, as several clinical trials have shown, certain bacteria might stimulate the innate immune response in ICI responders, leading to CXCL9 production in the TME and sensitization of anti–PD-1 antibody treatment through recruitment of tumor-specific CD8+ T cells." (PMID 35389889, 2022). "Furthermore, CCR5-CCL4/CCL5 and CXCR3- CXCL9/CXCL10/CXCL11/CXCL13 axis were significantly correlated with CD 4 T and CD 8 T cells, indicating that these interactions may be essential for the recruitment of the T lymphocytes into tumor." (PMID 35530341, 2022). "In addition, SHP2 inhibition increased expression of CXCR3 ligands, CXCL9 and CXCL10, in MIA PaCa-2-PBMCs co-culture, suggesting that upregulation of chemoattractant cytokines by inhibition of SHP2 may be a common phenotype in the tumor microenvironment." (PMID 33446805, 2021).
tumor (continued). "Interestingly, although higher levels of TILs and CXCL9 were protective factors of TNBC, the “TILs-high and CXCL9/13-high” did not display a significantly better survival, suggesting that there may be an intricate interaction in the tumor microenvironment." (PMID 33815462, 2021). "Changes in tumor-associated lymphocytes (e.g., CD3+, CD4+, and CD8+), upregulation of INF-gamma stimulated genes in tumor transcripts, and increase in chemokines (e.g., CXCL9 and CXCL10) were observed, while no significant change in PD-L1 expression under nivolumab treatment was reported." (PMID 32630154, 2020). "Also, treatment of CXCL9 could dose-dependently reduced the mRNA expression and secretion of anti-tumour cytokines from CD8+ cytotoxic T cells, including TNFα, IL2, and IFNγ, further proving that CXCL9 treatment could lead to cytotoxic T cell exhaustion and dysfunction." (PMID 31913856, 2020). "The increased production of IFN-γ by intratumoral lymphocytes could enhance the intratumoral expression of CXCL9 and CXCL10 and subsequent recruitment of the hetIL-15-expanded pool of circulating CXCR3+ lymphocytes, generating a positive amplification loop that limits tumor growth." (PMID 32461349, 2020). "The treatment increased the expression of IFNγ and CXCL9/CXCL10 in the tumor, as well as increased serum IFNγ/TNFα and expression of tumor-infiltrating lymphocytes, which may indicate the effectiveness of durvalumab/olaparib combination therapy in inducing an immune response in the tumor." (PMID 33327450, 2020). "Therefore, we suggest that in Bhi tumors, TIL-Bs might recruit CD8+ T cells via CXCL9 and crucially contribute to the survival of the CD8+ T cells in the tumor microenvironment due to the in situ secondary costimulation employing CD40L/CD40 and TNFR/TNF superfamily signaling pathways." (PMID 31623665, 2019). "The expression of the CXCL9 and CXCL10 chemokines, together with HLA class II, OX40L, and PD-L2 are suggestive of the presence of antigen-presenting cells in the microenvironment while TIM-3 expression may reflect an activated/dysfunctional phenotype of tumor-infiltrating T cells." (PMID 31888734, 2019). "Pathways involving tumor-expressed extracellular membrane-bound chemokines CXCL9, CXCL10, and CXCL11 were identified and show potential interactions in networks translating intracellular damage to extracellular signals that may stimulate immune recruitment and tumor cell death." (PMID 25952672, 2015). "Thus, CD4+ T cells may also mediate upregulated expression of angiostatic chemokines such as CXCL9, CXCL10, and CXCL14 that are capable of inhibiting tumor growth or may downregulate expression of the chemokine receptor CXCR2 or its many ligands that promote angiogenesis." (PMID 26618181, 2015). "Last, but not least, there is growing evidence that CXCL9/CXCL10/CXCR3 and CXCL16/CXCR6 are involved in tumor pathogenesis, so they probably represent pleiotropic chemokines at the crossroads of immunity and carcinogenesis." (PMID 41373861, 2025). "In human tumours, we also observed an enrichment of CCR7 cDC1s but not CXCL9 cDC1s within TCF1 regions, which suggests that discrete spatial co‐localisation is preserved across species." (PMID 40745918, 2025). "Depletion of resident macrophages reduces CXCL9 and MMP12 expression, alleviating renal injury without compromising anti‐tumor effects." (PMID 40810645, 2025). "Depletion of Ptdss1 in tumor cells increased expression of interferon-γ (IFN-γ)–regulated genes, including B2m, Cxcl9, Cxcl10, and Stat1, even in the absence of IFN-γ stimulation in vitro." (PMID 40929270, 2025). "In this work we identify CXCL9 as a candidate lymphocyte call-and-receive signal absent in GBM following a comprehensive chemokine screen of clinical tumor specimens." (PMID 38997283, 2024).